CXCR4 (C-X-C motif chemokine receptor 4)
Diseases named in the same sentence as CXCR4 in open-access papers (continued):
Sharing a sentence is not in itself a finding about the gene and the disease.
tumor (continued). "Epithelial cells from early tumours were unresponsive to any treatment suggesting that neither CXCR4 nor CCR7 in these cells can transduce the signal from their ligands." (PMID 34685420, 2021). "In fact, CXCR4, SPP1, ACKR3, CCL2, PTGS2, CD274 (PD-L1), CXCL11 were upregulated while CCL28, CCR1, CCR7 were down regulated in both comparisons (blue boxes), suggesting this as a signature specific of the core region of the tumor." (PMID 33066172, 2020). "When we considered the association between serum concentrations of the analyzed proteins and PC tumor stage according to TNM classification, we found that the serum levels of CXCR4, CRP and CEA were higher in advanced stage of disease in comparison to early PC." (PMID 32867211, 2020). "Importantly, MSCs possess several surface markers (e.g., CXCR4, CXCR12, and CCL2) that allow them to home to the tumor sites in response to chemokines secreted by the tumor cells." (PMID 32295145, 2020). "Corroborating this observation, preclinical studies in an autochthonous murine model of PDAC revealed that both pharmacological inhibition of CXCR4 and genetic ablation of CXCL12 producing CAFs led to a rapid accumulation of CD8+ T cells within the tumour and reduced tumour growth." (PMID 32967079, 2020). "Moreover, the immune checkpoints B7-H3/CD276 and OX40 were found to be significantly co-expressed with core EMT genes, TGFB1, CXCR4, IL10, and IL6 on tumor microenvironment as vascular endothelial and myeloid cells." (PMID 32708431, 2020). "We observed that FTY720 could increase CXCR4 internalization, and thereby reduce the receptor CXCR4 levels on the surface of microglia, leading to the inhibition of MAPK-mediated IL-6 release in the tumor microenvironment." (PMID 32194542, 2020). "Additional autoradiographic studies with appropriate CXCR4 IHC as well as H&E histology confirmed that 76Br-HZ270-1 radioactivity tracked-to and was localized-in brain CSF cisterns and not localized to CXCR4-expressing tumor." (PMID 32239371, 2020). "Endogenous tumor-reactive T cells are present within the human PDAC tumor microenvironment and can be reactivated by combined blockade of PD-1 and C-X-C chemokine receptor 4 (CXCR4)." (PMID 32987956, 2020). "CXCR4 is a critical receptor to modulate tumor-stromal interactions including cell invasion and migration, and therapeutic resistance, and blocking of CXCR4 by AMD3100 increases the anti-tumor effect of docetaxel in PCa patients with tumor metastasis." (PMID 33194726, 2020). "In addition, CXCR4 and CXCR5 expression levels were remarkably different in tumor differentiation (CXCR4, P < 0.001; CXCR5, P < 0.001)." (PMID 32896997, 2020). "Then we confirmed whether matrine can also affect CXCR4, MMP-2, and MMP-9 mRNA levels in tumor cells." (PMID 32630806, 2020). "Furthermore, CCL19/CCR7, CXCL12/CXCR4, and CCL20/CCR6 were shown to be potential new targets for tumor gene therapy in type 2 PRCC." (PMID 32775427, 2020). "However, at the invasive front of the tumor CD133+ cells are enriched for CXC-chemokine receptor 4 (CXCR4) and the CD133+CXCR4+ population is more migratory than CD133+CXCR4--." (PMID 33339340, 2020). "Combined expression of CAR and CXCR4 might, therefore, enable enhanced chemotaxis of CAR NK cells to the bone marrow allowing more efficient targeting of persistent tumor cells in the tumor niche environment." (PMID 32983147, 2020). "Histological analysis of primary tumors and metastases from a cohort of 56 patients revealed high levels of CXCR4 in tumor cells, but not in healthy head and neck tissue, which correlated with poor prognosis." (PMID 32296435, 2020). "Consistent with CXCR4 role in the mobilization and survival of endothelial cell precursors, AMD3100, an antagonist of this receptor administered to HIV-infected individuals, effectively impairs tumor vasculogenesis in pre-clinical models." (PMID 32528888, 2020).
tumor (continued). "Chemokines and their receptors play an important role in directing cognate T-APC interactions in lymph nodes and spleen (e.g., CCR7 and CCL21/19), or in bone marrow (e.g., CXCR4 and CXCL12 (SDF-1α/β), or attracting Treg cells towards tumor tissue (e.g., CCR2 and CCL2 (MCP-1))." (PMID 32155856, 2020). "Serum concentrations of both specific receptors for chemokines (CXCR4, p < 0.001 and CXCR2, p = 0.01) as well as the classical tumor marker (CEA, p < 0.001) and the marker of inflammation (CRP, p < 0.001) were statistically significantly higher in PC patients when compared to healthy volunteers." (PMID 32867211, 2020). "And CXCR4 positive cells increased expression of MMP9 and MMP15, which are known to play an important role in extracellular matrix remodeling during the process of tumor invasion and metastasis." (PMID 32232002, 2020). "In primary tumours, we observed a significant increase in the number of CXCR4+, but not of CXCR2+ cancer cells while the number of CXCR2+ TICs was also significantly increased in JL tumours." (PMID 32581213, 2020). "The CXCL12/CXCR4 interaction phosphorylates CXCR4, subsequently promotes calcium flux, and directly activates MAPK, PI3K, Wnt, and Sonic Hedgehog signaling pathways, thus inducing proliferation of various types of tumor cells." (PMID 33363463, 2020). "CD90+CXCR4+ present a better surface marker of CTSCs than CD133+CD90+, promoting the formation of tumor spheres in vitro, tumor development in primary and subsequent secondary and tertiary transplantation experiments, and distal metastatic tumors following subcutaneous transplantation." (PMID 32466488, 2020). "Although loss of CXCR4 results in neutrophil egress from the bone marrow, CXCR4 acquisition is relevant for neutrophil infiltration into the tumor; therefore, inhibiting the CXCL12/CXCR4 axis could also result in therapeutic effects." (PMID 33505304, 2020). "The biodistribution of labeled T22-GFP-H6-ATTO and T22-GFP-H6-S-Cy5 nanoparticles has been then compared to that of the non-labeled nanoparticle in different CXCR4+ tumor mouse models." (PMID 33105866, 2020). "Gemcitabine resistance may also be due to combined effects of C-X-C motif chemokine receptor 4 (CXCR4) and hedgehog pathways via bidirectional tumor-stromal crosstalk." (PMID 33198082, 2020). "The use of CXCR4 antagonist has the role of unmasking the tumor to immune attack by multiple mechanisms, such as decreasing the infiltration of MDSCs, increasing the ratio of CD8+ T cells to Treg cells and eliminating tumor revascularization." (PMID 32575838, 2020). "Furthermore, the dipeptidyl peptidase (DPP)-4 inhibitor, KR62436, promoted primary tumor growth, and lung metastasis via induction of the CXCL12/CXCR4/mTOR/EMT signaling axis in a syngeneic mouse model." (PMID 32245205, 2020). "PET imaging of CXCR4 expression in s.c. tumors was successful, but due to the hydrophilicity of the radiolabeled cyclam analogues and the presence of an intact BTB in the animal models, intracranial tumor visualization was poor." (PMID 32239371, 2020). "Furthermore, CXCR4 inhibition prevents migration of MCL cells beneath the stromal cells and abrogates microenvironment protection, making the tumor cells more accessible to chemotherapy." (PMID 32370190, 2020). "In summary, our analyses suggest that CXCR4 may affect the progression and prognosis of GC by influencing immune infiltration, TMB, CYT, tumor purity, and drug sensitivity." (PMID 32306562, 2020). "Therefore, CTHRC1 can participate in tumor cell migration and invasion through HIF-1α/CXCR4 signals in GC." (PMID 32848510, 2020). "Several studies have shown that the overexpression of CXCR4 has been found in NSCLC and may be related to tumor progression and prognosis." (PMID 32896997, 2020). "mAbs, such as BMS-936564/MDX-1338 and LY2624587, could also suppress CXCR4/CXCL12 signaling pathways and inhibit tumor growth and metastasis in different animal models both in vitro and in vivo." (PMID 33392074, 2020).
tumor (continued). "The absence of CXCR4 on the tumour plasma cell surface, while not being a strict predictive factor of extramedullary lesions, probably plays a role in the formation of extraosseous foci." (PMID 32321465, 2020). "Elevated expression levels of CXCR4, CXCR5 and CCR7 were found in tumor tissues (P < 0.001)." (PMID 32896997, 2020). "Interestingly, these pathways are utilized by a series of chemokines and their receptors, such as CCL20/CCR6, CCL25/CCR9, CXCL1/CXCR2, CXCL8/CXCR1-2, CXCL12/CXCR4, and CX3CL1/CX3CR1, to inhibit apoptosis and promote tumor cell growth and proliferation." (PMID 31991604, 2020). "Moreover, CXCR4 expression in cancer cells increased upon treatment with tumor necrosis factor α (TNF-α), released both by TAMs and tumor cells." (PMID 32784743, 2020). "In addition to TCR signaling pathways, the binding of CXCR4 and chemokine CXCL12 activated several pathways involved in the molecular mechanism of progression, angiogenesis, and metastasis in tumor." (PMID 32640634, 2020). "Only 36% of cases showed CXCR4 expression which was not significantly correlated with gender, age, tumor size, necrosis, stage and metastasis (P>0.05)." (PMID 31983166, 2020). "Low numbers of CXCR4+MET+CD44+ cells initiated tumor growth, while negative samples, with one exception, failed to do so." (PMID 32066735, 2020). "In hematological malignancies, as well as in solid tumors, the overexpression of CXCR4 is responsible for metastasis in organs expressing high CXCL12 levels (e.g., lymph nodes and BM), in addition to disease progression, increased tumor cell survival, and chemoresistance." (PMID 32260318, 2020). "Moreover, as activation of the CXCL12/CXCR4 axis stimulates VEGF and MMP production in mature endothelial cells, CXCR4 antagonists also inhibit tumor angiogenesis in animal models of human tumors." (PMID 32528888, 2020). "Because CXCR4 is induced in EWS cells exposed to hypoxia, a common condition of human tumor microenvironment, we investigated the contribution of the IGF2BP3/CD164/CXCR4 axis on CXCL12-evoked biological responses of EWS cells under normoxic (21% O2) or hypoxic conditions (1% O2)." (PMID 32719743, 2020). "In addition, CXCR4 and CXCR5 expression were significantly different in tumor differentiation (CXCR4, P < 0.001; CXCR5, P < 0.001)." (PMID 32896997, 2020). "However, further investigation indicated that SELNs induce the activation of NFκB, the expression and secretion of CXCL12, and stimulation of CXCR4/AKT survival pathway, resulting in protection of these tumor cells from death." (PMID 33363463, 2020). "Compared to Survivin/BIRC5 and TERT, the expression of CXCR4 resulted not adequately selective for tumour samples versus healthy tissues." (PMID 32152425, 2020). "However, significant differences were indicated only between serum levels of the analysed receptors (CXCR4 and CXCR2) in all the studied subgroups of PC patients (tumor stage, T, N, M factor) and control groups." (PMID 32867211, 2020). "The subsequent investigation of S1PR1 revealed that it might also be a prognostic gene in LUAD (in TCGA cohort and GSE72094), with interactions with some well-known tumor genes such as AKT1, STAT3 and CXCR4." (PMID 33628734, 2020). "CXCR4 is involved in MSC migration, and CXCR7 is involved in survival and paracrine actions of MSCs76,77, angiogenesis, modulation of the immune system and tumor invasion." (PMID 30872568, 2019). "FAP-positive CAFs in tumor stroma are the major source of C-X-C motif ligand 12 (CXCL12) in the tumor, and inhibition of its receptor, the C-X-C motif receptor 4 (CXCR4), induced T cell accumulation in the tumor and acted synergistically with anti-PD-L1 in diminishing cancer cells." (PMID 31540286, 2019).
tumor (continued). "A recent study showed that radiation induces tumor cells to release SDF-1α and platelet-derived growth factor-β, which bind to CXCR4 and platelet-derived growth factor receptor-βon circulating BMSCs, respectively; this results in the migration of BMSCs into the TME and promotes tumor growth." (PMID 30755239, 2019). "For instance, efficacy of anti-CXCR4 ADCs did not correlate with antigen density on tumour cells: all cell lines with detectable surface CXCR4 demonstrated sensitivity to anti-CXCR4 ADCs." (PMID 30792442, 2019). "Taken together with the in vitro CXCR4 expression in H1155 results, this data suggests that tumours developed after ADC 713 treatment arose through selection of the CXCR4− subset of H1155 cells and not due to resistance of CXCR4+ cells to the ADC." (PMID 30792442, 2019). "Furthermore, tumor stroma cell-secreted SDF1 assists CXCR4 activation in tumor cells and CXCR4-induced HH expression stimulates CAF recruitment." (PMID 31921628, 2019). "This implies that CXCR4 inhibitors can be administered after RTCT with the expectation of equivalent if not better tumour control, which has the benefit of minimising concerns about overlapping toxicity." (PMID 31239542, 2019). "Furthermore, production of PGE2 by MDSC stimulates the expression of C-X-C chemokine receptor type 4 (CXCR4) and Stromal cell-derived factor 1 (CXCL12) responsiveness, facilitating the migration of MDSC into sites of inflammation and tumor." (PMID 31275327, 2019). "As TCF12 regulated CXCR4 and CXCL12 expression, an in vitro HUVECs tube formation assay was conducted to explore whether TCF12 plays a functional role in tumor angiogenesis." (PMID 31534521, 2019). "For example, engineering CXCL12 ligand, i.e. C-X-C motif receptor (CXCR)-4, into CAR-T cells could increase the percentage of CAR molecules reaching reach tumor cells." (PMID 31619289, 2019). "This response could be attributed to the binding of environmental CXCL12 to CXCR4 on CLL B cells and the subsequent activation of the AKT/FoxO3a/Bim axis within tumor cells." (PMID 30927928, 2019). "To verify the inhibitory effect of losartan on CXCR4, we treated MDA-MB-231 cells with SDF-1α and found that SDF-1α-treated tumor cells showed a distinct cytoskeletal redistribution of F-actin stress fibres and lamellipodia formation beginning 20 min after SDF-1α exposure by phalloidin staining." (PMID 31219799, 2019). "In addition, we examined the effect of the AGTR1 inhibitor losartan on CXCR4/SDF-1α expression in mouse models and tumor cells." (PMID 31219799, 2019). "Survival analysis revealed that metastasis-free survival MFS was shortest if CXCR4 was total nuclear localization in the primary tumor, whereas none of the patients in this cohort with cytoplasmic CXCR4 relapsed." (PMID 30177838, 2019). "In addition, TCF12 participates in the angiogenesis of endothelial cells in the tumor microenvironment via regulation of CXCL12 and CXCR4-mediated bFGF expression." (PMID 31534521, 2019). "This is not surprising, given that human CXCR4 is only expressed in a minority of cancer cells and this tumour is partially resistant to the microtubule inhibitor paclitaxel." (PMID 30792442, 2019). "Furthermore, the AMD3100 (CXCR4 inhibitor)-induced blocking of M2-like TAM skewing not only increased survival, but also showed enhanced inhibition of tumor growth." (PMID 31174610, 2019). "CXCR4 distributed in the blood vessels in the stroma was thought to be involved in tumor progression and survival, consistent with the absence of CXCR4 in the stromal blood vessels of the nontumor area." (PMID 31336612, 2019). "CXCL12 is expressed by microvascular endothelial cells and stimulated proliferation of GBM progenitor cells but not differentiated tumor cells via CXCR4, whereas ACKR3 was not involved." (PMID 30813533, 2019).
tumor (continued). "Moreover, over-activation of the TGF-β pathway promotes CXCR4 expression in HCC cells and confers CXCR4-dependent migration characteristics to cells to leave the primary tumour." (PMID 31752959, 2019). "CXCR4 plays a crucial role in tumor angiogenesis required for OSCC progression, whereby TAITN induced by the CXCR4 antagonist could be an effective anti-angiogenic therapeutic strategy in OSCC treatment." (PMID 31336612, 2019). "Together, our results show that a functional crosstalk between PDGFR/SDF-1 is induced in tumor cells at late stages of mouse and human skin SCC progression, in order to induce autocrine activation of SDF-1/CXCR4 signaling and to promote tumor cell invasion and metastasis." (PMID 30874597, 2019). "Stromal cells surrounding primary tumours or metastatic lesions may secrete high levels of CXCL12/SDF1 and induce CXCR4 expression in tumour cells supporting the hypothesis that CXCR4 is important for tumour growth." (PMID 31877673, 2019). "Thus, besides decreasing CXCR4 expression and altering CLL cell trafficking, ibrutinib, and SEL24-B489 also inhibited CXCL12/CXCR4-mediated CLL cell-tumor microenvironment cross-talk signaling, such as induction of cell survival and CD20 upregulation." (PMID 30787933, 2019). "Therefore, we assessed whether correlation with worse PS (and thus greater tumour load) could be found with different levels of those exosomal proteins resulted to stratify patients in different clusters after hierarchical cluster analysis: EpCAM, CXCR4, CD81 and CD9." (PMID 31048929, 2019). "CXCR4 was not uniformly distributed in all tumor blood vessels, but it was partially localized at the constricted and branched parts of the blood vessels." (PMID 31336612, 2019). "Importantly, we discovered that MDMX correlates with the increased transcription of CXCR4 and PTGS2 in tumor tissue." (PMID 30642351, 2019). "CXCR4 antagonists dramatically reduce AML load in mice previously engrafted with primary human AML without influencing the engraftment of normal hematopoietic progenitors, probably because tumor cells express higher levels of CXCR4 than normal cells." (PMID 31709192, 2019). "Furthermore, ulocuplumab, an anti-CXCR4 monoclonal antibody (mAb), modifies the RNA expression of signals that mediate EMT, reducing tumor size and tumor BM homing." (PMID 31323969, 2019). "Given the often metastatic and tumour-initiating activity of CXCR4+ cancer cells, inclusion of anti-CXCR4 ADC as part of the therapy regimen might increase benefit, particularly in tumours sensitive to microtubule inhibitor agents." (PMID 30792442, 2019). "The interaction of CXCR4 with its ligand, CXCL12, activates a cascade of cellular signaling promoting the survival, proliferation, adhesion, and migration of the CXCR4-expressing tumor cells." (PMID 31428099, 2019). "In the present study negative correlations were observed between tumor grading and SST2A and CgA expression, and a positive association with CXCR4 and Ki-67 expression." (PMID 30867449, 2019). "Moreover, CXCR4, with its ligand CXCL12, played a critical role in tumor progression induced by TCF12 via activation of the MAPK/ERK and PI3K/AKT signaling pathways." (PMID 31534521, 2019). "Both the PDGF/PDGFR and SDF-1/CXCR4 signaling pathways are involved in mediating EMT and angiogenesis, and thus, the regulation of tumor growth, invasion, and metastasis, but this is the first time the secretion of PDGFR-α (by protein microarray and ELISA) from cancer cells has been detected." (PMID 30483898, 2019). "Co-injection of AMD-3100 confirmed CXCR4-specificity by reducing the tumor uptake of these ligands without substantially influencing clearance." (PMID 31022852, 2019). "We here aimed to evaluate (i) the subtumor distribution of CXCR4 in human clinical specimens of OSCC and (ii) the effects of a CXCR4 antagonist AMD3100, so-called plerixafor, on inhibition of tumor angiogenesis and tumor growth in mice xenografted with OSCC cells." (PMID 31336612, 2019).